AR (androgen receptor)
Diseases named in the same sentence as AR in open-access papers (continued):
Sharing a sentence is not in itself a finding about the gene and the disease.
tumor (continued). "Metformin treatment of androgen-dependent PCa cells xenografted into mice significantly reduced tumor growth, AR and PSA expression, and mTORC1/CREB signaling." (PMID 37573301, 2023). "The role of androgen receptor (AR) signaling in tumor initiation and progression is indeed complex, with studies reporting contrasting findings." (PMID 37564195, 2023). "These combinatorial strategies are aimed at disrupting the immunosuppressive effects of AR signaling while unleashing the full potential of the immune system to mount an effective anti-tumor response." (PMID 37646236, 2023). "Increased AR expression allows PCa to circumvent low androgen levels by hypersensitizing tumor cells to androgens, promoting disease progression." (PMID 37455903, 2023). "Among ADTs, bicalutamide belongs to the first generation of non-steroidal antiandrogen drugs, which can effectively block androgen receptor (AR) activity and tumor invasion in androgen-responsive PCa and has been widely used in clinical practice." (PMID 37143720, 2023). "Conversely, 20–25% of CRPC cases harbor AR gene rearrangements concurrent with AR amplification, often with multiple AR gene rearrangement events in a tumor." (PMID 37636316, 2023). "Our study demonstrates a tumor-promoting role of SMAD3 in PCa cell growth dependent on the AR pathway." (PMID 36727462, 2023). "Androgen Receptor (AR) overexpression enables the survival and proliferation of tumor cells in limited-androgen conditions during androgen suppression treatment." (PMID 37894414, 2023). "The AR in normal prostate epithelial cells act as a tumor suppressor, suppressing these cells’ indefinite proliferation." (PMID 37103355, 2023). "A high expression level (mfIHC score) of PR, AR, GATA3, and TROP2 was significantly linked to low pT stage and low tumor grade (p ≤ 0.0002 each)." (PMID 38137396, 2023). "RNA was extracted from tumor tissues, and qPCR analyses of AR and AR-V7 regulated genes revealed that there were significant decreases in TMPRSS2 and EDN2 expressions in the bicalutamide and α-mangostin groups." (PMID 37046780, 2023). "This allows suggesting that a higher expression of AR and ER in tumor tissue is correlated with a greater effectiveness of antihormonal therapy." (PMID 36766353, 2023). "In the AR-high setting where AR repressed ERα signaling, enzalutamide antagonized AR, promoting ERα signaling, while RAD140, a selective AR agonist, activated AR signaling and suppressed AR-high tumor growth by inhibiting ER52." (PMID 37684290, 2023). "This late-stage disease is a major burden for hormonal therapy because the tumour cells are able to proliferate independently of androgen receptor (AR) signalling." (PMID 37778382, 2023). "In vivo PET and biodistribution studies on male mice bearing an LnCaP (AR+) xenograft showed an approximately three-times-higher tumor uptake for 18F-enzalutamide than for [18F]FDHT." (PMID 37175938, 2023). "Heterogeneous tumor tissues were collected for nucleoplasmic separation, and the levels of AR proteins in the nucleus and plasma were detected by western blot." (PMID 36744249, 2023). "The androgen receptor (AR) is emerging as a promising tumor target for improved diagnostics and therapeutic options due to its significant role in the etiology and progression of different cancer types." (PMID 37370896, 2023). "High AR-expressing tumors showed reduced macrophage infiltration into the tumor microenvironment; this finding was consistent with CIBERSORTx and FCM analysis results." (PMID 36721218, 2023). "Jointly, these studies strongly suggest that AR signaling is pro-tumorigenic in GBM and that AR antagonists curtail tumor cell growth in vitro and in vivo." (PMID 37626712, 2023). "The further understanding of AR’s mechanism in tumor cells can improve drug efficacy as well as the prognoses of patients suffering from TNBC." (PMID 38067367, 2023).
tumor (continued). "In vivo, ARD-69 degrades tumor AR after a single intraperitoneal (IP) injection at 50 mg/kg given to mice xenografted with VCaP-derived tumors." (PMID 36991452, 2023). "At initial diagnosis, over 90% of PCa cases are androgen-dependent, making ADT in the reduction in circulating and tumor androgen levels and inhibition of androgen receptor (AR) signaling a good treatment option for PCa." (PMID 37240449, 2023). "By crossing this model with Hi-Myc mice (ARR2/probasin-Myc) and inducing AR deletion, they observed an increased epithelial luminal cell proliferation and tumour progression, suggesting a tumour-suppressing role of stromal AR." (PMID 36482187, 2023). "MYB also exhibits a positive correlation with AR expression and both display higher expression in advanced tumor stages." (PMID 38089573, 2023). "We compared the membranous expression of β-catenin, cadherins and Wnt antagonist Dkk1 in tumour tissue as well as expression of hormone receptors (ER, PR and AR) against nuclear expression of β-catenin." (PMID 36969079, 2023). "A classic example of transcription factors regulating ADAR, AR served as a transcriptional activator of the ADAR1 promoter to promote HCC tumor growth both in vitro and in vivo." (PMID 36660243, 2023). "This study shows that the glycosylation profile of tumor cells demonstrate significant change as a result of hormonal therapy and the development of AR-independent PCa." (PMID 36828904, 2023). "The comparison of AR transcriptomes between normal prostate and samples from different tumor stages indicates dramatic differences." (PMID 36768610, 2023). "These new molecules disrupt the liquid–liquid phase separation (LLPS) propensity, protein–protein interactions and transcriptional activity of AR and AR-Vs and showed anti-tumor effects in animal models, including those expressing AR-Vs." (PMID 38201511, 2023). "In the context of AR inhibition, recent studies have focused on the role of seviteronel in AR+ tumor cells." (PMID 37371867, 2023). "Previously, our group demonstrated that increased cholesterol levels contribute to p160 coactivator overexpression and indirectly upregulate AR expression, favoring tumor progression." (PMID 37298588, 2023). "Since the vascular endothelial growth factor (VEGF) is a target gene of AR in the liver and plays an important role in tumor angiogenesis, the increased transcriptional activity of AR leads to higher risk of developing HCC in HCV-infected patients." (PMID 37508414, 2023). "We have previously observed crosstalk between EGFR and extranuclear steroid receptors (AR and ER) in tumor cells (MCF-7 and LNCaP)." (PMID 37370896, 2023). "FISH for AR also yielded an AR ecDNA pattern in the majority of nuclei from LuCaP 35 tumor cells grown in intact mice, as well as LuCaP 35CR tumor cells grown in castrated mice." (PMID 37636316, 2023). "A recent study on genomically characterized patient-derived xenografts (PDX) observed increases in PSMA and androgen receptor (AR) mRNA as well as tumor microdensity after ADT in castration-sensitive models." (PMID 36161511, 2023). "For example, in cases where ER is present, AR has exhibited tumor suppressor activity, and selective AR modulators are proving to be more effective treatment options as compared to AR inhibitors." (PMID 38067367, 2023). "Although the primary tumor of YCU-SDC-14 was partially positive for AR, all our PDXs, PDOs and PDXOs of YCU-SDC-14 were AR negative." (PMID 36538240, 2023). "X15695 effectively inhibited tumor growth over vehicle upon oral administration (30 mg/kg/day), albeit less effectively compared with enzalutamide (10 mg/kg/day), identifying X15695 as a weaker AR antagonist in this tumor model." (PMID 37520743, 2023). "The tumor-to-normal brain SUVmean uptake ratio correlated positively with the AR protein expression, and this correlation was statistically significant (Pearson’s correlation coefficient r = 0.84; p < 0.002)." (PMID 37175938, 2023).
tumor (continued). "To confirm the presence of multiply-rearranged AR gene structures emerging in LuCaP 105CR tumor tissue using an orthogonal method, we performed optical genome mapping." (PMID 37636316, 2023). "Unique to PCa is its reliance on the AR to regulate tumor progression via transcriptional regulation of AR targeted genes and the activation of AR-targeted signaling pathways." (PMID 37455903, 2023). "Excitingly, mice with LNCaPabl subcutaneous tumours treated with combination AR and PKA oligodeoxynucleotides showed complete tumour remission." (PMID 37830741, 2023). "An interrogation of primary BlCa tumor transcript data (cBioportal, 413 samples) uncovered a strong statistical correlation between AR and mTOR expression, supporting our results linking AR and mTOR." (PMID 36720985, 2023). "More recent studies find that cytoplasmic AR levels do not differ between tumors and adjacent normal tissue, but nuclear AR expression is significantly higher in tumor cells." (PMID 37626712, 2023). "AR gene amplification was detected in 27% of GBMs from men and 38% of tumors from women, and further analysis shows that AR mRNA is overexpressed in 93% of tumor samples." (PMID 37626712, 2023). "Induction of knockdown of AR in LuCaP35 by Dox treatment resulted in a reduction in tumor growth and demonstrated the dependency of LuCaP35 cells on the AR signaling pathway." (PMID 37999103, 2023). "Most castration-resistant tumours express a functional AR and therefore, the term androgen-independent prostate cancer has been replaced with CRPC." (PMID 37830741, 2023). "Initially, PCa is reliant on androgens and AR signaling for tumor growth and progression and is characterized by a rising prostate-specific antigen (PSA) level in humans, a marker not typically expressed in dog PCa." (PMID 37189720, 2023). "Several other studies also show that androgen ablation elicits enhanced AKT activity, which, in turn, impaired the anti-tumor efficacy of AR inhibitors in preclinical models." (PMID 36768610, 2023). "Expression of COMMD3 in luminal-A-like tumours was directly associated with markers of luminal differentiation: c-KIT, ELF5, androgen receptor and tubule formation (the extent of normal glandular architecture; p < 0.05)." (PMID 37072858, 2023). "Catalytic Top2 inhibitors disrupt AR signaling and reduce tumor formation in castration-resistant xenografts, suggesting their potential application in the treatment of castration-resistant cancers." (PMID 36678591, 2023). "Together, these studies confirm that AR-SV expression reprograms cellular transcription, elevating the expression of genes that promote tumor initiation and progression." (PMID 37626712, 2023). "LuCaP 105CR tumor tissue also displayed emergence of myriad smaller AR protein species with molecular weights ranging from ∼60–80 kDa, at least 2 of which were identified as AR-V7 and AR-V9." (PMID 37636316, 2023). "In the presence of DHEA, an FDA approved Bruton’s tyrosine kinase (BTK) and BMX inhibitor, zanubrutinib, effectively blocked androgen receptor–positive (AR-positive) xenograft tumor growth in castrated mice." (PMID 36647834, 2023). "Collective data support NEPC arising as a mechanism of resistance to AR therapies with loss of AR protein expression and/or canonical AR signaling in NEPC tumors and acquisition of alternative lineage programs that drive tumor growth." (PMID 37546702, 2023). "The androgen receptor (AR) was expressed in 40% of tumor cells, predominantly in spindle and solid epithelial components." (PMID 37401932, 2023). "A newer drug, galeterone, also blocks CYP17, AR, and the transcriptional activity of this receptor in the nucleus of tumor cells." (PMID 36769263, 2023). "This upregulation of AR expression in PCa is suggested to be a compensatory mechanism aimed at counterbalancing the reduced levels of testosterone necessary for initiating tumor growth." (PMID 38068717, 2023).
tumor (continued). "Prior studies have also shown that estrogen can increase apoptosis in RCC, while androgen and the androgen receptor (AR) can promote various aspects of tumor progression, including stemness, angiogenesis, proliferation, migration, and invasion of RCC." (PMID 37715192, 2023). "This variant lacks the ligand-binding domain, leading to the constitutive activation of the AR in an androgen-independent manner, thereby promoting tumor growth." (PMID 37894767, 2023). "Although, through recent years, more potent drugs have been incorporated, this chronic AR signaling inhibition inevitably led the tumor to an incurable phase of castration resistance." (PMID 37189723, 2023). "Activation of the AR pathway promotes the secretion of chemokines and cytokines by tumor cells, which in turn attract immune cells to tumor sites." (PMID 37646236, 2023). "Analyses of tumor biopsies demonstrated that patients with ≥10% positive cells for ER or AR by IHC had longer PFS than patients with ER and AR < 10% positive." (PMID 37210417, 2023). "In xenograft models of CRPC and enzalutamide-resistant PC patients, GLUT1 inhibition significantly reduced tumor volume and displayed synergistic effects with androgen receptor (AR)-targeted therapy." (PMID 36768924, 2023). "The univariable logistic analysis showed that time interval, tumor size, molecular subtypes, AR status, the largest diameter decrease and change in blood perfusion were significantly associated with pCR (p < 0.1)." (PMID 37035201, 2023). "Inhibition of FASN activity in castration-resistant cancer cell lines results in a decrease in tumor development, increased apoptosis, altered lipidome, decreased lipid storage, and increased AR expression." (PMID 36769263, 2023). "As CT7001 mechanistically functions independently of the AR LBD, unlike all approved AR-targeted compounds, it is a good therapeutic candidate for CRPC tumours with AR reactivation." (PMID 37076563, 2023). "Biomarker evaluation including sTIL, AR, Ki-67 and PD-L1 was performed on core biopsy materials as a representation of the entire tumor; therefore, limited sampling is an intrinsic limitation of this neoadjuvant study." (PMID 37444385, 2023). "The enrichment of nuclear mTOR, AR and SMARCD1 in MDA PCa 2b has indicated a more aggressive tumor phenotype in AA PCa vs. EA PCa (i.e., LNCaP, an androgen-dependent EA PCa with much lower nuclear mTOR, AR, and SMARCD1)." (PMID 38023145, 2023). "Myeloid cells, macrophages, and lymphocyte recruitment and growth in the prostate gland can promote DNA double-strand breaks and androgen receptor activation in prostate epithelial cells, accelerating tumor development." (PMID 37426635, 2023). "MiR-320a-3p (genomic location: 8p21.3) seems to mediate the effect of histone deacetylase inhibitors in PCa by targeting AR expression, having, apparently, a tumor-suppressive role." (PMID 37240449, 2023). "Accordingly, impaired anti-tumor activity was stated in male mice with elevated AR levels upon BRAF and MEK1/2 inhibition compared to female ones." (PMID 37686465, 2023). "More interestingly, an international multicenter study evaluated AR status in tumor tissues of 1407 TNBC patients from six different countries." (PMID 37099044, 2023). "We analyzed the anti-oncogenic effects of 5α-reductase inhibition on tumor progression in both control BCa cells and AR-overexpressing cells by measuring proliferation, migration, and the expression levels of cancer-related signaling pathways and target genes." (PMID 36800968, 2023). "In fact, a discrepancy between AR expression profile in common BC cell lines and human tumors was previously identified, and strong tumor β2-AR expression was correlated with increased disease-free survival." (PMID 37189370, 2023). "Inflammatory cytokines such as IL-1 and IL-6 can activate estrogen or androgen receptor signaling on tumor cells, linking inflammation to tumor growth and endocrine resistance." (PMID 38033495, 2023).
tumor (continued). "AR showed a high correlation with TOMM20 expression in the tumor specimens of PCa patients and PCa cells." (PMID 37563661, 2023). "We have shown that X15695 inhibits proliferation of tumor cells that express ERα and AR as well as the transactivation function of these two receptors but its effect is more profound on ERα compared with the AR-expressing tumor cells." (PMID 37520743, 2023). "On the other hand, the relative tumor area in hep-c-MYC/AR-FL male mice were morphologically larger than that in hep-c-MYC male mice." (PMID 36746917, 2023). "YY1BM specifically binds to the transcription factor YY1, blocking its interaction with the androgen receptor (AR) and leading to the downregulation of eukaryotic elongation factor 2 kinase (eEF2K) expression in tumor cells through the AR signaling pathway." (PMID 37444616, 2023). "Compared to PC-9/AR/vector and PC-9/AR/shYAP1 xenograft, tumor growth of YAP1 knocked down xenograft was significantly retarded." (PMID 37215986, 2023). "Routine immunohistochemistry was also performed on tumor tissues and was stained with an AR antibody, showing that there were decreases in the expression of AR in the bicalutamide and α-mangostin groups." (PMID 37046780, 2023). "“AR-high” group of patients have tumor AR levels greater than median AR (−0.718) for the entire cohort, while “AR-low” group of patients have tumor AR levels lower than the median AR." (PMID 36833272, 2023). "This unique tumour metabolism is partly driven by the AR-regulated mitochondrial pyruvate carrier (MPC)." (PMID 36151426, 2023). "The tumor AR and ER expressions were measured immunohistochemically from biopsies within 8 weeks of the PET acquisition." (PMID 37175938, 2023). "PD-L1 expression in the tumor cells has been correlated with AR levels and the tumor proliferation index (assessed by Ki67 staining), and PD-1 promoter methylation has been associated with AR activity." (PMID 37511177, 2023). "Tumor growth of the androgen-dependent LuCaP35 PDX was significantly inhibited following depletion of the androgen receptor (AR) in vivo." (PMID 37999103, 2023). "The analysis of the relationship between AR and ultrasound characteristics in different molecular subtypes showed that: in the Luminal A subtype, with the different expression of AR, the echo pattern of the tumor was different (p = 0.024)." (PMID 36929229, 2023). "The expressions of c-MYC, AR-V7, and AR-FL in the developed tumor foci were confirmed by immunohistochemistry at 20 days post-injection (dpi)." (PMID 36746917, 2023). "IL-6 is increased in PCa, induces EMT and metastasis, increases the expression of androgen receptor, and induces infiltration of T cells into the tumour microenvironment." (PMID 38137361, 2023). "Directly targeting androgen ligands with androgen-inhibiting drugs (e.g., chemical castration) or decreasing their production via surgical castration has been utilized over the last 80 years in an attempt to suppress AR signaling and PCa-tumor progression." (PMID 37189720, 2023). "On the other hand, the selective androgen receptor modulator enobosarm decreased tumor growth in preclinical models." (PMID 37210417, 2023). "Tumor size expansion was significantly reduced at later times in mice treated with all three AR inhibitors." (PMID 37838724, 2023). "NXTAR is another tumor suppressor lncRNA that modulates expression of androgen receptor (AR) and resistance to enzalutamide." (PMID 37025585, 2023). "We found that metformin treatment in a clinically relevant dose of ~ 70 μM decreased size, weight, and tumor volume in AR/STAT3 expressing 22Rv1 cells but was ineffective for PC3 xenografts, which lack STAT3." (PMID 37573301, 2023). "This protein is an androgen receptor chaperone which can even be exploited as a marker of tumor progression and as a potential therapeutic target." (PMID 38012666, 2023).